S100B (S100 calcium binding protein B)
Diseases named in the same sentence as S100B in open-access papers (continued):
Sharing a sentence is not in itself a finding about the gene and the disease.
breast carcinoma (26 papers, 2011 to 2026). "For example, in breast cancer, high S100B expression is associated with reduced migratory capacity and improved prognosis, indicating that not all S100 members universally promote metastasis." (PMID 41404073, 2025). "At present, no studies have examined the association between elevated serum S100B and brain metastases or the use of serum S100B as a screening tool for brain metastases in breast cancer." (PMID 24179506, 2013). "Meanwhile, compared with normal breast epithelium cells, the expression levels of IKZF2, NAB1, S100B were significantly downregulated in breast cancer cells." (PMID 40520263, 2025). "The previous study had demonstrated that a high S100B expression predicted a good distant metastases-free survival in all patients with breast cancer, which was in line with our result." (PMID 34053447, 2021). "According to the literature, all 3 identified LNM-upregulated genes, i.e. ATG10, GATA3 and S100B, are considered markers of breast cancer cells and their invasive potential." (PMID 33658651, 2021). "To test this, we analyzed protein expression of S100A6 and S100B via IHC of TMAs containing patient sample biopsies from different stages of breast cancer totaling 160 cores." (PMID 32211331, 2020). "Taken together, these molecular studies provided us with a model of S100β production in endocrine resistant breast cancer where endocrine treatment can induce rapid tyrosine kinase signaling to induce HOXC11/SRC-1 transcriptional activation of S100β." (PMID 28399921, 2017). "Together these data establish S100β as an output of the endocrine resistance network and support its use as a serum marker of the emergence of endocrine-related metastatic disease in breast cancer patients." (PMID 28399921, 2017). "As the possibility of assessing S100β levels in patient serum substantially enhances its clinical utility, a clinical assay suitable for use in patients with breast cancer was therefore developed." (PMID 28399921, 2017). "We investigate the mechanism of S100β production in endocrine resistant breast cancer and demonstrate that inhibition of the Src kinase pathway with the kinase inhibitor dasatinib can reduce tumor progression in vivo." (PMID 28399921, 2017). "Here we examine the prognostic potential of serum S100β as a monitoring tool for tumor response in patients with breast cancer on endocrine treatment." (PMID 28399921, 2017). "However, in the TNBC subtype, we observed an opposite expression pattern: CACNA1H and KCNJ11 were significantly downregulated compared to other breast cancer subtypes, whereas S100B showed markedly elevated expression." (PMID 40606662, 2025). "Studies have shown that S100B is a good predictor of disease-free survival of breast cancer." (PMID 39493752, 2024). "The results showed that the expression of PLK1 and IFNG in human breast cancer cells were significantly higher than in human normal mammary epithelial cells; while the expression of S100B and IRS2 were significantly lower than in human normal mammary epithelial cells." (PMID 39314848, 2024). "S100B expression has been negatively correlated with lymph node metastasis, inhibition of cell migration, better overall survival in luminal B breast cancer patients, and being a good distant metastases-free survival biomarker." (PMID 36338974, 2022). "In addition, S100B can suppress the migratory capacity of ER-negative breast cancer cells, and the expression of S100B is a predictive marker for metastasis in breast cancer." (PMID 31690011, 2019). "The expression of S100B mRNA was correlated with better survival in luminal B type breast cancer." (PMID 28051137, 2017). "An appropriate cut-off of S100β serum levels in patients (0.13 μg/L) was established in a training set and verified in a validation study (n = 76, all breast cancer patients; n = 59, ER-positive breast cancer patients)." (PMID 28399921, 2017).
breast carcinoma (continued). "S100β is a member of the S100 family of calcium-binding proteins, several of which, including S100A7 and a truncated form of S100P, have been associated with progressive breast cancer." (PMID 28399921, 2017). "In endocrine resistant xenografts and tumor explants from patients with endocrine resistant breast cancer, combined endocrine and dasatinib treatment reduced tumor proliferation and down-regulated S100β protein expression in comparison to endocrine treatment alone." (PMID 28399921, 2017). "This mode of S100B activity may be specific to breast cancer." (PMID 39335163, 2024). "Therefore, breast cancer patients with elevated S100β may benefit from combined endocrine and kinase inhibitor treatment." (PMID 28399921, 2017). "Moreover, endocrine resistant breast cancer patients with elevated S100β may benefit from combined endocrine and tyrosine-kinase inhibitor treatment." (PMID 28399921, 2017). "Compared with normal breast epithelium cells, RFX5, VEGFA were upregulated in breast cancer cells, IKZF2, NAB1, S100B were downregulated in breast cancer cells while F2R, S1PR2 showed no significance." (PMID 40520263, 2025). "The expression levels of S100B and IRS2 in breast cancer tissues were significantly lower than those in the paired adjacent normal tissues." (PMID 39314848, 2024). "PLK1, IFNG, S100B, and IRS2 were expressed at significantly different levels between breast cancer and normal breast tissues." (PMID 39314848, 2024). "Further publications covering this connection identified S100B as a serum marker in endocrine-resistant breast cancer and elevated S100B serum levels as a negative prognostic value for breast cancer." (PMID 32722137, 2020).
multiple sclerosis (26 papers, 2010 to 2025). A progressive autoimmune disorder affecting the central nervous system resulting in demyelination. "In multiple sclerosis, elevated S100B levels are detected in the CSF during the acute phase and evidence shows that levels decrease following immunosuppressive therapy: for example, in patients treated with natalizumab." (PMID 40362691, 2025). "Studies also confirmed serum/CSF S100B protein increasing during relapses in multiple sclerosis and, as an important addition in MS diagnosis, we note the establishment of the kappa free light chain index as a quantitative alternative to OCBs." (PMID 40362691, 2025). "For example, elevated S100B levels are also observed in patients with multiple sclerosis, amyotrophic lateral sclerosis, or cancer, as S100B is found in all neuronal tissue thus leading to a low specificity." (PMID 39091977, 2024). "Changes in CSF and serum S100B are related to the inflammatory response in multiple sclerosis, and extracellular levels of S100B appear to have prognostic value for outcomes in traumatic brain injury." (PMID 38068900, 2023). "Clinically, S100B was first found to be elevated in the CSF of multiple sclerosis (MS) patients during acute phases of the disease, while it was low during the stationary phases." (PMID 37569895, 2023). "Levels of As, Pb, and Cd measured in the blood of the patients with multiple sclerosis positively correlated with serum S100B levels." (PMID 36613911, 2022). "The relevance of S100B in multiple sclerosis pathology brought anemerging curiosity highlighting its use as a potential therapeutic target toreduce damage during the multiple sclerosis course, namely during inflammatoryrelapses." (PMID 35620168, 2022). "Our preclinical data reinforcethe involvement of S100B in pathology and the possibility to repurpose pentamidineas a novel potential therapy for multiple sclerosis." (PMID 35620168, 2022). "Our study unveiledand explored the importance of the S100B molecular targeting through pentamidine asa positive strategy to prevent multiple sclerosis-driven neuroinflammation, promoteremyelination and therefore fasten recovery." (PMID 35620168, 2022). "Overall, our results reinforce the involvement of S100B in the development of animal models of multiple sclerosis and propose AA targeting the S100B protein as a focused potential drug to be considered for multiple sclerosis treatment." (PMID 34948360, 2021). "This study investigates the effect of arundic acid (AA), a known inhibitor of astrocytic S100B synthesis, in the chronic experimental autoimmune encephalomyelitis, which is another mouse model of multiple sclerosis usually studied." (PMID 34948360, 2021). "Pentamidine is a small molecule able to bind and inhibit S100B involved in the modulation of disease progression in a relapsing-remitting experimental autoimmune encephalomyelitis mouse model of multiple sclerosis." (PMID 33114371, 2020). "Overall, our results indicate that pentamidine targeting the S100B protein is a novel potential drug to be considered for multiple sclerosis treatment." (PMID 32197530, 2020). "Increased expression of S100B and its specific receptor for advanced glycation end products (RAGE) has been described in patients with multiple sclerosis (MS), being associated with an active demyelinating process." (PMID 33100970, 2020). "The glial protein S100B, which belongs to a calcium binding protein family, is up-regulated in neurological diseases, like multiple sclerosis or glaucoma." (PMID 30319357, 2018). "Several studies have suggested that S100B protein has a role in the pathogenesis of some autoimmune neuropsychiatric diseases, such as multiple sclerosis (MS) and neuropsychiatric systemic lupus erythematosus (NPSLE)." (PMID 22420334, 2012). "A number of correlative evidence proposes that S100B high levels may play a promoting role also in multiple sclerosis (MS)." (PMID 40649727, 2025).
multiple sclerosis (continued). "They found that the level of S100B was significantly increased in the cerebrospinal fluid of patients with multiple sclerosis in the acute phase, while the level of S100B protein was found to be lower in the stable phase of the disease, suggesting that this protein is not limited to nerve tissue." (PMID 35615727, 2022). "Altogether, this study strengthened the crucial role of S100B in multiplesclerosis pathology and highlighted the possibility to use pentamidine as a therapyto reduce damage and improve recovery of multiple sclerosis lesions, with high drugrepurposing potential." (PMID 35620168, 2022). "The aim of this study is to investigate the possible role of a small molecule able to bind and inhibit S100B, pentamidine, in the modulation of disease progression in the relapsing–remitting experimental autoimmune encephalomyelitis mouse model of multiple sclerosis." (PMID 32197530, 2020). "Thus, pentamidine targeting S100B is considered a novel approach for multiple sclerosis treatment." (PMID 33114371, 2020). "It has been demonstrated that S100B actively participates in neuroinflammatory processes of different diseases of the central nervous system (CNS), such as experimental autoimmune encephalomyelitis (EAE), a recognized animal model for multiple sclerosis (MS)." (PMID 40649727, 2025).
COVID-19 (25 papers, 2021 to 2026). A disease caused by infection with severe acute respiratory syndrome coronavirus 2. "Elevated S100B levels were linked to worse clinical status, with significantly higher levels observed in COVID-19 patients who required intensive care unit (ICU) oxygenation compared with those managed without ICU support." (PMID 41585373, 2025). "The consistent association of elevated IL-6, IL-10, and S100B levels with severe disease outcomes points to their potential use in stratifying COVID-19 patients based on risk." (PMID 41585373, 2025). "The research is preliminary, aimed at assessing the feasibility of studying NE, NSE, and S100B as elements of a prognostic model for long-term complications caused by COVID-19." (PMID 39519343, 2024). "The presented study shows that NE, NSE, and S100B are potential components of a prognostic model for long-term complications caused by COVID-19 in patients with comorbid conditions such as type 2 diabetes (T2DM) or advanced diabetic nephropathy (NfT2DM)." (PMID 39519343, 2024). "Increased levels of D-dimer, IL-6, pentraxin-3, and S100B were specifically associated with mortality in male critical COVID-19 patients only." (PMID 39507250, 2024). "As mentioned with previous brain injury biomarkers, serum S100B has also been associated with disease severity in COVID-19 patients." (PMID 36268187, 2022). "Herein, we aimed to evaluate the association between serum NfL and S100B with the presence of neurological manifestations and functional prognosis in COVID-19 patients, while also considering comparison of biomarker levels with other clinical and laboratory variables." (PMID 39779630, 2025). "Moreover, the study reveals consistent results for crucial biomarkers, such as IL-6 and S100B, exhibiting low variability (I2 < 30%) among the studies, which suggests dependable associations with COVID-19 severity, particularly in pneumonia cases." (PMID 41585373, 2025). "In addition, an increase surge in S100A8 and S100B is associated with mild to severe COVID-19 pathogenesis." (PMID 35892571, 2022). "Serum S100B levels were found to be associated with COVID-19 severity." (PMID 34836309, 2021). "The aim of this study was to evaluate the diagnostic utility of classical inflammatory and metabolic markers, as well as potential variables associated with COVID-19 condition, such as neutrophil elastase (NE), neuron-specific enolase (NSE), and S100B protein." (PMID 41930248, 2026). "Several follow-up studies covering a time frame from 24 to 48 weeks in COVID-19 patients also reported normalized levels of S100β, GFAP, and NfL." (PMID 41516418, 2026). "We aimed to evaluate the association between serum neurofilament light chain (NfL) and S100B biomarkers with the presence of neurological manifestations and functional prognosis in COVID-19 patients." (PMID 39779630, 2025). "These markers reflect the immune dysregulation and hyperinflammatory states that exists in severe COVID-19, confirming IL-6’s central role and extending attention to IL-10, IL-8, and S100B as complementary markers of disease severity." (PMID 41585373, 2025). "On the other hand, serum S100B levels were markedly higher in both early- and late-stage COVID-19 patients compared with healthy individuals." (PMID 41585373, 2025). "Although the highest S100B concentration in the group of T2DM patients whose blood was collected after COVID-19 was only 700 pg/mL, this protein was detectable at CS100B ≥ 7.8 pg/mL in 79% of participants in the group." (PMID 39519343, 2024). "We measured two independent biomarkers of BBB permeability in peripheral blood, astrocyte-derived EVs and S100B, investigating the potential longitudinal effects of COVID-19 on the BBB." (PMID 39349618, 2024). "The study results indicated that S100B concentration was measurable (c ≥ 7.8 pg/mL) in 49 out of 62 patients with T2DM who had recovered from COVID-19, representing a significant 79% of the group." (PMID 39519343, 2024).
COVID-19 (continued). "It was also shown that in patients with metabolic disorders after COVID-19, S100B was more frequently detected—in other cases, the protein level was low, beyond the sensitivity of the test." (PMID 39519343, 2024). "Based on the analysis, it was found that in the group of patients with NfT2DM who had recovered from COVID-19, 5.5% exhibited elevated levels of all three measured proteins (NE, S100B, and NSE) above the established reference values." (PMID 39519343, 2024). "Research has also demonstrated a correlation between increased levels of S100B in serum and both disease severity and inflammatory markers in COVID-19 patients." (PMID 39349618, 2024). "In particular, COVID-19 patients exhibited increased serum S100B levels upon hospital admission compared to healthy controls, showing a positive correlation with disease severity." (PMID 39451987, 2024). "Demonstrating differences in the prevalence of NE, NSE, and S100B in individuals who recovered from COVID-19 with T2DM and NfT2DM makes these proteins important components of the developing predictive model for early detection of PCS." (PMID 39519343, 2024). "In the group of patients with T2DM who had recovered from COVID-19, there was also a significantly higher occurrence of elevated levels above the established reference values for NE and S100B." (PMID 39519343, 2024). "Based on the obtained results, it can be stated that S100B concentration was detected in the serum of 6 out of 55 (10.9%) patients with NfT2DM who had recovered from COVID-19." (PMID 39519343, 2024). "Elevated levels of S100B were found more frequently in patients with T2DM after COVID-19, while NE and NSE were elevated in those with NfT2DM." (PMID 39519343, 2024). "A prospective study of patients with COVID-19 showed that plasma brain injury markers, including S100B, were higher in males than in females, but this difference was not statistically significant." (PMID 38783266, 2024). "We also observed lower levels of autoantibodies against NMDA receptors (IgA), glutamic acid decarboxylase 65 (IgG), amyloid β peptide (IgG), tau protein (IgG), enteric nerve (IgG), and S100-B (IgG) in COVID-19 patients compared with healthy controls." (PMID 36832180, 2023). "Lower IgA autoantibody levels against NMDA receptors, and IgG autoantibodies against glutamic acid decarboxylase 65, amyloid β peptide, tau protein, enteric nerve, and S100-B were detected in COVID-19 patients versus healthy controls." (PMID 36832180, 2023). "The S100B homodimer is also positively correlated with COVID-19 patient ferritin levels but negatively correlated with lymphocyte counts and percentages." (PMID 36017003, 2022). "RAGE ligands (AGE, S100A8/A9, S100B, amyloid-beta, LPA, HMGB1, C1q, suPAR) and sRAGE are elevated in CKD, COVID-19 and many of the co-morbidities that increase the risk of disease severity." (PMID 36017003, 2022). "Report show that levels of serum S100B were not correlated with neurological symptoms overall in acute phase COVID-19 patients, but did find marginally elevated levels of S100B in patients with more than one neurological symptom." (PMID 36268187, 2022). "We found that levels of BIMs, specifically MAP2, NSE and S100β were significantly elevated in the acute phase of COVID-19." (PMID 34838058, 2021). "Elevated serum levels of the S100B protein were found in COVID-19 patients, reflecting an increased blood–brain barrier permeability." (PMID 34836309, 2021). "We found that MAP2, NSE and S100B were higher after COVID-19 indicative of brain injury after COVID-19." (PMID 34838058, 2021). "However, the data using S100B to predict COVID-19 or to classify disease severity are contradictory." (PMID 39779630, 2025). "In addition, in acute COVID-19 populations, S100B concentrations correlated significantly with organ injury indicators and inflammation markers, including C-reactive protein (CRP)." (PMID 40048451, 2025).